POU5F1P3 (POU class 5 homeobox 1 pseudogene 3)
Synonyms: POU5FLC12; OTF3L; POU5F1L
Gene: Processed pseudogene on chromosome 12 (8,133,772 to 8,134,849, reverse strand). Ensembl gene ENSG00000235602.
Diseases named in the same sentence as POU5F1P3 in open-access papers:
POU5F1P3 is named in the same sentence as 17 diseases in open-access papers, as found by Europe PMC text mining. Sharing a sentence is not in itself a finding about the gene and the disease. The quoted sentences say what the papers report.
colorectal cancer (2 papers, 2018 to 2023). A primary or metastatic malignant neoplasm that affects the colon or rectum. "The co-expression profile of POU5F1P3 was retrieved across 65 colorectal cancer and 65 normal sample." (PMID 30287838, 2018). "POU5F1P3 and POU5F1P4 are oncogenes in kidney and colorectal cancer, respectively." (PMID 37667739, 2023). "Similarly, the three OCT4 pseudogenes normally function as tumor suppressor genes in various cancer types, while POU5F1P3 in kidney cancer and POU5F1P4 in colorectal cancer may function as oncogenes." (PMID 30287838, 2018).
breast carcinoma (1 paper, 2018). "Similar to OCT4 and POU5F1P1, the expression level of POU5F1P3 was also low in breast cancer tissues, which was associated with poor patient survival." (PMID 30287838, 2018). "Particularly, in breast cancer, expression of OCT4, POU5F1P3, and POU5F1P4 was down-regulated compared to in normal tissue." (PMID 30287838, 2018).
embryonal carcinoma (1 paper, 2018). A non-seminomatous malignant germ cell tumor characterized by the presence of large germ cells with abundant cytoplasm resembling epithelial cells, geographic necrosis, high mitotic activity, and pseudoglandular and pseudopapillary structures formation. "For instance, POU5F1P3 was highly expressed in undifferentiated NT2 (NTERA-2) cells, a known pluripotent human embryonal carcinoma cell line, while expression of POU5F1P3 was dramatically down-regulated upon enhancement of neural differentiation." (PMID 30287838, 2018).
gastric cancer (1 paper, 2018). A primary or metastatic malignant neoplasm involving the stomach. "Similar survival patterns were observed for gastric cancer patients with OCT4/POU5F1P3, OCT4/POU5F1P4, POU5F1P1/POU5F1P3, POU5F1P1/POU5F1P4, or POU5F1P3/POU5F1P4 co-occurrence." (PMID 30287838, 2018).
germ cell tumor (1 paper, 2016). A benign or malignant, gonadal or extragonadal neoplasm that originates from germ cells. "We found a correlation between PIM1/2 expression and VENTX, SOX15, UTF1, NANOG, POU5F1P4, POU5F1P3, and POU5F1B expression in male germ cell tumors." (PMID 27901106, 2016).
ovarian carcinoma (1 paper, 2018). A malignant neoplasm originating from the surface ovarian epithelium. "By contrast, high expression levels of both OCT4 and POU5F1P3 were associated with poor survival outcomes in patients with ovarian cancer." (PMID 30287838, 2018). "Additionally, in ovarian cancer, OCT4 was co-expressed with DNAJBI3, C2orf88, and several genes with lower correlation values compared to the three pseudogenes (POU5F1P1, POU5F1P3, and POU5F1P4) at seminoma." (PMID 30287838, 2018).
seminoma (1 paper, 2018). A radiosensitive malignant germ cell tumor found in the testis (especially undescended), and extragonadal sites (anterior mediastinum and pineal gland). "OCT4 was found to be highly co-expressed with its three pseudogenes (POU5F1P1, POU5F1P3, and POU5F1P4) in seminoma." (PMID 30287838, 2018).
teratocarcinoma (1 paper, 2023). A germ cell tumor characterized by the presence of an embryonal carcinoma component and a teratoma component. "In human, the chromosome region where NANOG is located also contains DPPA3, POU5F1P3 and another pluripotency factor, GDF3, and collectively is called a ‘hotspot for teratocarcinoma’ owing to the high rate of chromosomal abnormalities." (PMID 36621005, 2023).
cancer (1 paper, 2018). A tumor composed of atypical neoplastic, often pleomorphic cells that invade other tissues. "To confirm the expression status of the POU5F1P3 gene in cancer, we applied the Oncomine database in various cancer types with a significant p-value." (PMID 30287838, 2018). "We obtained similar results through bioinformatics analysis, which demonstrated that expression of POU5F1P1 and POU5F1P3 regulated cancer progression and clinical outcomes of patients." (PMID 30287838, 2018). "Not only undifferentiated cells, but also several cancer cells expressing POU5F1P3 gene, may influence patient survival." (PMID 30287838, 2018). "Furthermore, the interactions among OCT4, POU5F1P1, POU5F1P3, and POU5F1P4 might be associated with the progression of various types of cancers." (PMID 30287838, 2018). "Among them, we examined OCT4 and three pseudogenes (POU5F1P1, POU5F1P3, and POU5F1P4) because of their high expression possibility in cancer." (PMID 30287838, 2018). "The results of our systematic analysis agree with studies showing that OCT4 and its pseudogenes (POU5F1P1, POU5F1P3, and POU5F1P4) are expressed in various cancer cells and affected patient survival." (PMID 30287838, 2018). "Among the eight pseudogenes, we selected three pseudogenes (POU5F1P1, POU5F1P3, and POU5F1P4) along with OCT4 for bioinformatics analysis because of their expression availability in various cancers." (PMID 30287838, 2018). "Interestingly, the multivariate survival analysis revealed a significantly poor prognosis when OCT4/POU5F1P3 expression was high/low or low/high compared to the high/high or low/low group, suggesting that partial-co-occurrence of OCT4/POU5F1P3 may regulate cancer prognosis." (PMID 30287838, 2018).
POU5F1P3 also shares sentences with these, for which no sentence is quoted: fatty liver disease (1 paper); Immunodeficiency (1); kidney cancer (1); liver disease (1); lymphoma (1); testicular cancer (1); testicular tumor (1); tumor (1).